TLE1 (TLE family member 1, transcriptional corepressor)
Description:
Transcriptional corepressor that binds to a number of transcription factors. Inhibits NF-kappa-B-regulated gene expression. Inhibits the transcriptional activation mediated by FOXA2, and by CTNNB1 and TCF family members in Wnt signaling. The effects of full-length TLE family members may be modulated by association with dominant-negative AES. Unusual function as coactivator for ESRRG.
Synonyms: ESG1; GRG1; ESG; TLE-1
Tractability: Small molecule: a structure with a bound ligand is known; it has a high-quality binding pocket. PROTAC: UniProt records ubiquitination sites on it; ubiquitination databases record sites on it; its protein half-life has been measured.
Gene: Protein-coding gene on chromosome 9 (81,582,313 to 81,689,681, reverse strand). Ensembl gene ENSG00000196781.
Subcellular location: Nucleus
Subcellular location (Human Protein Atlas): Nucleoplasm
Pathways (Reactome):
Signal Transduction: Deactivation of the beta-catenin transactivating complex; Formation of the beta-catenin:TCF transactivating complex; NOTCH1 Intracellular Domain Regulates Transcription; Repression of WNT target genes
Cell-Cell communication: Negative Regulation of CDH1 Gene Transcription
Gene Ontology:
Molecular function: DNA-binding transcription factor binding; identical protein binding; protein binding; transcription corepressor activity
Biological process: negative regulation of anoikis; negative regulation of canonical NF-kappaB signal transduction; negative regulation of DNA-templated transcription; negative regulation of Wnt signaling pathway; positive regulation of gene expression; animal organ morphogenesis; negative regulation of canonical Wnt signaling pathway; signal transduction; regulation of DNA-templated transcription
Cellular component: beta-catenin-TCF complex; cytosol; nucleoplasm; nucleus; transcription regulator complex
Genetic constraint (gnomAD): Loss-of-function variants: 20 observed, 84.79 expected, observed/expected ratio (o/e) 0.24, 90% interval 0.17 to 0.34. The upper end of that interval is the gene's LOEUF score, 0.34, which puts it in group 1 of 6, group 1 being the genes least tolerant of losing a copy. Missense variants: 792 observed, 1,009.4 expected, observed/expected ratio (o/e) 0.78, 90% interval 0.74 to 0.83. Synonymous variants: 444 observed, 405.03 expected, observed/expected ratio (o/e) 1.1, 90% interval 1.01 to 1.19.
Homologues: Orthologues: chimpanzee TLE1 (100% identical), macaque TLE1 (100% identical), dog TLE1 (99% identical), pig TLE1 (99% identical), guinea pig TLE1 (99% identical), mouse Tle1 (98% identical), rat Tle1 (98% identical), tropical clawed frog tle1 (95% identical), Caenorhabditis elegans unc-37 (29% identical). Paralogues in human: TLE4 (87% identical), TLE3 (80% identical), TLE2 (67% identical), TLE7 (19% identical), TLE6 (19% identical), TLE5 (17% identical).
Diseases named in the same sentence as TLE1 in open-access papers:
TLE1 is named in the same sentence as 105 diseases in open-access papers, as found by Europe PMC text mining. Sharing a sentence is not in itself a finding about the gene and the disease. The quoted sentences say what the papers report.
synovial sarcoma (68 papers, 2009 to 2025). "This robust TLE1 expression adheres to the established diagnostic criteria for synovial sarcoma, thereby enhancing the precision of the diagnosis." (PMID 38234938, 2023). "Overall, the combined IHC profile with TLE1 positivity provided useful diagnostic information and aids in the proper diagnosis of synovial sarcoma." (PMID 38156143, 2023). "This systematic review examines the potential role of TLE1 as a diagnostic biomarker for the synovial sarcoma." (PMID 32322158, 2020). "In the deletion of chromosome 9, TLE1 appears to be a gene of interest; it has also been reported as a risk factor for synovial sarcoma." (PMID 32211073, 2020). "In spite of the variable data regarding the diagnostic value of TLE1 in synovial sarcoma, our analysis indicates that the preponderance of evidence favors TLE1 as a legitimate biomarker for this disease." (PMID 32322158, 2020). "Based on their titles and abstracts, sixteen relevant citations evaluating TLE1 as a diagnostic marker in synovial sarcoma were identified in our literature query." (PMID 32322158, 2020). "We therefore sought to conduct a meta-analysis with the goal of assessing the value of TLE1 as a diagnostic marker for synovial sarcoma." (PMID 32322158, 2020). "The association of TLE1 and tumors was first detected in synovial sarcomas through gene expression profiling, and TLE1 was found to be profoundly involved in the Wnt/β-catenin signaling pathway in synovial sarcomas." (PMID 30053869, 2018). "TLE1 is therefore a robust diagnostic immunohistochemical marker for synovial sarcoma diagnosis and is a potential therapeutic target." (PMID 27852056, 2017). "Here we report use of the proximity ligation assay to confirm the oncogenic association of SS18-SSX with its co-factor TLE1 in multiple human synovial sarcoma cell lines and in surgically-excised human tumor tissue." (PMID 27120803, 2016). "Recently; TLE1 has been described as a diagnostic marker for synovial sarcoma which is claimed to be more sensitive and specific than others." (PMID 23800262, 2013). "Typical morphology and focal cytokeratin/EMA positivity should alert to this tumor, and TLE-1, a relatively sensitive marker for synovial sarcoma, should be used to avoid the diagnostic dilemma." (PMID 22966471, 2012). "Other TLE family members have been implicated in tumorogenic pathways, and TLE1 when overexpressed leads to lung adenocarcinoma in mice and also has been confirmed as a biomarker able to differentiate synovial sarcomas." (PMID 19309506, 2009). "TLE1, a recognized marker linked with synovial sarcoma, was found to be expressed positively." (PMID 38156143, 2023). "Tle1 is notable not only for being an expression neighbor of ctag1b/a in the GSEA-identified module but also a network neighbor that has been proposed as a diagnostic immunohistochemical marker for synovial sarcoma." (PMID 35664317, 2022). "In particular, overexpression of the known marker TLE1 in synovial sarcoma could be recovered, which underlines the reliability of this system." (PMID 36230659, 2022). "Identification of the networks in which TLE1 is involved, from a molecular standpoint, may help develop further diagnostic tests and novel targeted therapies for synovial sarcoma." (PMID 32322158, 2020). "Several studies have explored the mechanisms underlying TLE1 function in synovial sarcoma." (PMID 27852056, 2017). "Interestingly, a gender bias has been observed in the association of TLE1 and different cancers such as acute myeloid leukemia and synovial sarcoma." (PMID 25663950, 2015). "Commonly utilized markers include Bcl-2, which exhibits substantial cytoplasmic positivity, and TLE1, which is very sensitive and specific for synovial sarcomas." (PMID 40718269, 2025). "In contrast, synovial sarcoma exhibits a biphasic or monophasic spindle cell morphology with specific markers like TLE1, CD99, and Bcl-2, which aid in differentiation." (PMID 40578241, 2025).
synovial sarcoma (continued). "Strong and diffuse staining for TLE1 is often considered a characteristic feature of synovial sarcomas." (PMID 40171344, 2025). "Synovial sarcomas are strongly positive for TLE1 on IHC, while other sarcomas and carcinomas can rarely express TLE1." (PMID 40171344, 2025). "Diffuse staining for TLE1 is a consistent feature of synovial sarcoma, which is used to differentiate it from other soft tissue sarcomas and is an important part of immunohistochemical panel." (PMID 40747128, 2025). "Tumour cells were immunoreactive for transducer-like enhancer of split 1 (TLE1) and cluster of differentiation 99 (CD99) with a score of 4+ and 3+, susceptible and specific for monophasic synovial sarcoma diagnosis." (PMID 38410005, 2024). "Subsequently, the postoperative pathology reveals the presence of monophasic synovial sarcoma, specifically confirmed by positive expression of Vimentin, TLE1, and BCL-2 in immunohistochemical analysis." (PMID 39494240, 2024). "These panels should include a variety of makers to ensure accurate diagnosis, as seen by the presence of TLE1 in synovial sarcoma or MDM2 in liposarcoma." (PMID 38156143, 2023). "Positive staining for TLE1 on cell block sections is seen in synovial sarcomas, while detection of EWSR1 rearrangement is helpful in diagnosing Ewing sarcoma/primitive neuro-ectodermal tumors." (PMID 37510144, 2023). "Among the 6 synovial sarcoma cases, all exhibited positivity with TLE1 and three cases demonstratedCD99 positivity." (PMID 37908610, 2023). "A noteworthy finding, in this case, was the strong positive expression of TLE1, which stands as a highly specific marker for synovial sarcoma." (PMID 38234938, 2023). "TLE1-positivity aids in the diagnosis of synovial sarcoma since it is a specific marker for this cancer." (PMID 38156143, 2023). "Other tumors, such as synovial sarcoma, can be distinguished from DF as it shows TLE1 positivity and SS18 rearrangement, while spindle cell rhabdomyosarcoma of the jaw shows TFCP2 rearrangement." (PMID 37602060, 2023). "Synovial sarcoma displayed both monophasic and biphasic growth patterns and TLE1 expression, with NKX 2.2 variation suggesting tumor heterogeneity." (PMID 38234938, 2023). "In synovial sarcoma, positive expression of TLE1, and localized weak expression of NKX 2.2 are common." (PMID 38234938, 2023). "The metastatic lymph node showed diffuse and strong nuclear expression by TLE1 immunostaining, confirming the metastatic synovial sarcoma to the lymph node." (PMID 35029897, 2022). "The expression of TLE1 is found in synovial sarcomas, and the TLE family can be a predictive marker for tumor diagnosis and a marker for treatment by indicating expression in various tumors." (PMID 36620623, 2022). "This reflects the reliability of this assay, as TLE1 is an already established marker for SyS, being overexpressed in the nuclei of synovial sarcoma cells." (PMID 36230659, 2022). "Our performed transcriptome profiling revealed robust results, and we were able to retrieve the known significant overexpression of TLE1 in synovial sarcoma." (PMID 36230659, 2022). "UZLX-STS7SynSa showed bundles of spindle cells and synovial sarcoma-specific TLE-1 immunopositivity and SS18 rearrangement." (PMID 35453612, 2022). "The expression of the transducin-like enhancer of split-1 (TLE1) serves as a biomarker for the diagnosis of synovial sarcoma." (PMID 33509178, 2021). "TLE1 expression was also seen in 53 of 143 (37%) non-synovial sarcoma, such as malignant peripheral nerve sheath tumors, neurofibromas and schwannomas." (PMID 34103053, 2021). "Recently, TLE1, a Groucho/Transducin-like enhancer of split TLE families, was found to be a diagnostic marker for synovial sarcoma." (PMID 34669095, 2021). "Poorly differentiated synovial sarcomas have variable and diffuse cytokeratin positivity and strong nuclear TLE-1 expression." (PMID 34722090, 2021).
synovial sarcoma (continued). "TLE1 has been used as a immunohistochemical marker for Synovial Sarcoma, an adult soft tissue sarcoma." (PMID 32033399, 2020). "Upregulation of ATF2 and TLE1 is important in the development of human synovial sarcoma and recruitment of TLE1 to the ATF2 binding locus downregulates expression of the tumor suppressor EGR1." (PMID 32019274, 2020). "In conclusion, TLE1 is a sensitive and specific marker for synovial sarcoma that can aid in its diagnosis." (PMID 32322158, 2020). "High-grade MLPS requires a differential diagnosis from poorly differentiated synovial sarcomas that lack lipoblasts and an arborizing capillary vascular pattern and are diffusely positive for TLE1 and SS18-SSX." (PMID 32867125, 2020). "Monophasic synovial sarcomas show more uniform nuclei with wiry stromal collagen and are diffusely positive for TLE1 and SS18-SSX and focally positive for cytokeratin and EMA." (PMID 32867125, 2020). "In accordance with this, expression of Atf2 and Tle1 was increased, while that of Egr1 was suppressed in mouse synovial sarcoma." (PMID 32019274, 2020). "Due to its high sensitivity and specificity, absence or presence of TLE1 on histology will aid in excluding or confirming the diagnosis of synovial sarcoma." (PMID 32322158, 2020). "Gene expression profiling studies have consistently shown the TLE family of genes, TLE1 in particular, to be overexpressed in the nuclei of synovial sarcoma cells." (PMID 32322158, 2020). "Poorly differentiated synovial sarcomas show strong and diffuse positivity for TLE1 and SS18 gene fusions." (PMID 32867125, 2020). "The last gene from this group—TLE1 is a specific biomarker of synovial sarcoma and subset of melanomas." (PMID 32455542, 2020). "In this case, synovial sarcoma was one of the differentials and interestingly it showed moderate to strong nuclear immunoreactivity to TLE1 in which rendered more challenges to the pathologist." (PMID 32212796, 2020). "According to the study by Kosemehmetoglu and colleagues, TLE1 expression was seen in 53 of 143 (37%) non-synovial sarcoma, with 36 such cases (25%) showing 2-3+ positivity." (PMID 31893185, 2019). "Twenty-four out of twenty-five (96%) cases of synovial sarcoma (SS) showed a 3+ Transducin-like enhancer of split 1 (TLE1) expression." (PMID 31893185, 2019). "A study from India in 2012 established TLE1 sensitivity for the diagnosis of synovial sarcomas to be 95.2%." (PMID 31893185, 2019). "We evaluated the frequency and intensity of TLE1 staining in synovial sarcomas and other soft tissue lesions." (PMID 31893185, 2019). "In cancer, TLE1 has oncogenic functions in lung cancer and synovial sarcoma in addition to tumor-suppressing activity in hematologic malignancies." (PMID 31379926, 2019). "Seven of the 98 cases (7%) of carcinomas showed TLE1 expression, highlighting a potential pitfall in the IHC interpretation for diagnosis of synovial sarcoma, thus making a combination of morphology and immunohistochemistry mandatory for diagnosis." (PMID 31893185, 2019). "Histologically, CCSK can mimic myxoid variant of synovial sarcoma (SS); however, the double positivity for CD99 and TLE1 in SS helps in excluding CCSK." (PMID 30410809, 2018). "They reported that TLE1 monoclonal and polyclonal antibodies gave intense and/or diffuse nuclear staining in 91 out of 94 molecularly confirmed synovial sarcoma patients." (PMID 29751751, 2018). "The use of recently identified antibodies, such as STAT6 for solitary fibrous tumor and TLE1 for synovial sarcoma, are helpful in some settings." (PMID 28145886, 2017). "The transcriptional co-repressor TLE-1 (Transducin-Like Enhancer of Split 1) has been used previously as a marker of synovial sarcoma and other sarcomas of peripheral nerve sheath origin, so we tested a purified sarcoma subset with an anti-TLE-1 antibody." (PMID 28403214, 2017).
synovial sarcoma (continued). "The pro-survival function of TLE1 has also been observed in malignant cells, particularly in synovial sarcoma cells and breast cancer cells." (PMID 29069783, 2017). "Many studies have demonstrated a relationship between TLE1 and various types of cancer (e.g. synovial sarcomas and lung cancer)." (PMID 27852056, 2017). "First, TLE1 is aberrantly expressed or upregulated in various types of human cancer including synovial sarcoma, breast and lung cancer." (PMID 29069783, 2017). "When this association is disrupted by specific knockdown of TLE1, ATF2 or SS18-SSX, synovial sarcoma cell lines undergo apoptosis, indicating this complex association is important for tumor cell survival." (PMID 28056055, 2017). "SS18-SSX/TLE1 complex assembly following HDAC inhibition was assessed by proximity ligation signal in five synovial sarcoma cell lines and was confirmed by co-immunoprecipitation." (PMID 27120803, 2016). "Quantification of SS18/TLE1 PLA signals in synovial sarcoma cell line nuclei is more than 10-fold higher than the level seen in control cell lines." (PMID 27120803, 2016). "Chromatin immunoprecipitation revealed a decrease in HDAC1 and H3K23me3 at the EGR1 promoter, a known target for repression by the SS18-SSX/TLE1/ATF2 complex consistent with a disruption of the biologic effects on SS18-SSX target genes in synovial sarcoma." (PMID 27120803, 2016). "In this study, the proximity ligation assay was applied to a neoplasm driven by a fusion oncoprotein, in this case confirming the key SS18-SSX interaction with TLE1 in synovial sarcoma cells and patient samples." (PMID 27120803, 2016). "Nuclear proximity ligation signal is detectable between SS18 and TLE1 in all six tested synovial sarcoma patient derived cell lines: SYO-1 (SS18-SSX2), FUJI (SS18-SSX2), MoJo (SS18-SSX1); Yamato-SS (SS18-SSX1), and ASKA-SS (SS18-SSX1); and CME-1 (SS18-SSX2)." (PMID 27120803, 2016). "The top three available compounds capable of disrupting the SS18-SSX/TLE1 proximity ligation signal were validated in multiple synovial sarcoma cell lines." (PMID 27120803, 2016). "Dissociation of the SS18-SSX/TLE1 complex following HDAC inhibition correlates with apoptotic induction in synovial sarcoma cell lines." (PMID 27120803, 2016). "When this association is disrupted by specific knockdown of TLE1, ATF2 or SS18-SSX, synovial sarcoma cell lines are observed to undergo apoptosis, indicating this complex association is important for tumor cell survival." (PMID 27120803, 2016). "In an excised pulmonary metastasis, SS18-SSX/TLE1 complex co-localization signal is detected exclusively in synovial sarcoma tissue nuclei while the adjacent normal lung tissues are negative." (PMID 27120803, 2016). "In order to visualize SS18-SSX/TLE1 co-localization in synovial sarcoma in situ, we set-up a proximity ligation assay (PLA) using antibodies specifically recognizing SS18 and TLE1." (PMID 27120803, 2016). "TLE1 is an additional sensitive immunohistochemical tool for identifying synovial sarcoma and all of Scheithauer’s intra-neural synovial sarcomas expressed TLE1." (PMID 24131748, 2013). "The sensitivity of TLE1 for synovial sarcoma has been challenged, however, and one group of researchers found that 30% of MPNSTs also labeled with TLE1." (PMID 24131748, 2013). "In addition, the first case was focally reactive to TLE-1, raising the possibility of synovial sarcoma, which can also show nuclear beta-catenin reaction." (PMID 41246587, 2025). "Diffuse and strong expression of TLE-1 as wells as focal expression of multiple epithelial markers strongly suggest the diagnosis of synovial sarcoma, and rhabdoid differentiation can also be seen in synovial sarcoma." (PMID 35125107, 2022). "TLE1 is a member of the TLE family of genes that encode Groucho-like transcriptional corepressors and is one of the most frequently overexpressed genes in synovial sarcoma." (PMID 32322158, 2020).